TRIM61 (tripartite motif containing 61)
Synonyms: RNF35
Tractability: No criterion of Open Targets' tractability assessment is met for any kind of drug.
Gene: Protein-coding gene on chromosome 4 (164,954,446 to 164,977,668, reverse strand). Ensembl gene ENSG00000183439.
Subcellular location (Human Protein Atlas): Endoplasmic reticulum; Nucleoli fibrillar center
Gene Ontology:
Molecular function: ubiquitin protein ligase activity; zinc ion binding
Biological process: innate immune response; regulation of gene expression
Cellular component: cytoplasm
Genetic constraint (gnomAD): Loss-of-function variants: 0 observed, 3.42 expected, observed/expected ratio (o/e) 0, 90% interval 0 to 0.87. That is too few expected variants to judge how well the gene tolerates losing a copy. Missense variants: 17 observed, 89.73 expected, observed/expected ratio (o/e) 0.19, 90% interval 0.13 to 0.28. Synonymous variants: 4 observed, 31.23 expected, observed/expected ratio (o/e) 0.13, 90% interval 0.062 to 0.29.
Homologues: Orthologues: guinea pig TRIM61 (66% identical), mouse Trim61 (52% identical). Paralogues in human: TRIM60 (64% identical), TRIM75 (48% identical), TRIM39 (33% identical), TRIM68 (31% identical), TRIM38 (30% identical), TRIM58 (29% identical), TRIM6 (29% identical), TRIM11 (28% identical), TRIM27 (28% identical), TRIM21 (28% identical), TRIM4 (27% identical), TRIM26 (27% identical), and 68 more.
Diseases named in the same sentence as TRIM61 in open-access papers:
TRIM61 is named in the same sentence as 1 disease in open-access papers, as found by Europe PMC text mining. Sharing a sentence is not in itself a finding about the gene and the disease. The quoted sentences say what the papers report.
cancer (2 papers, 2014 to 2022). A tumor composed of atypical neoplastic, often pleomorphic cells that invade other tissues. "While three of the chimeras (ACTB->POTEM, ACTB->POTEE and SP100->HMGB1) have been found in normal population, three of the chimeras (C2orf27A->NBEA, HILPDA->EFCAB3, FARSB->TRIM61) were previously identified only in cancer samples." (PMID 25133550, 2014). "On the contrary, TRIM23, TRIM61 and TRIM58 have lower expression in cancer." (PMID 36461099, 2022).